MIR384 (microRNA 384)
Synonyms: hsa-mir-384; MIRN384
Gene: MicroRNA gene on chromosome X (76,919,273 to 76,919,360, reverse strand). Ensembl gene ENSG00000283242.
Gene Ontology:
Biological process: miRNA-mediated post-transcriptional gene silencing